BDNF (brain derived neurotrophic factor)
Diseases named in the same sentence as BDNF in open-access papers (continued):
Sharing a sentence is not in itself a finding about the gene and the disease.
Anxiety (continued). "More recent studies in rodents have shown that DSS-induced depressive-like and anxiety-like behaviors correlate with gut microbiota composition, apoptosis, synaptic damage, neuroinflammation, as well as BDNF levels." (PMID 40077572, 2025). "Pharmacological manipulation confirms the involvement of BDNF/TrkB signaling, while knockdown of astrocytic BDNF further impairs synaptic function and exacerbates stress-induced anxiety." (PMID 40777598, 2025). "Previous research has identified neurotrophic factors, such as brain-derived neurotrophic factor (BDNF) and nerve growth factor (NGF), as biomarkers associated with temperament traits like emotional instability and anxiety-proneness." (PMID 40308388, 2025). "Chronic anxiety elevates glucocorticoids, inhibiting trabecular meshwork phagocytosis and downregulating BDNF." (PMID 41234418, 2025). "To investigate the involvement of this pathway in CRS-induced anxiety, we examined hippocampal BDNF and TrkB expression using quantitative PCR and Western blot analysis." (PMID 40777598, 2025). "These epigenetic modifications result in reduced expression of BDNF IV and IX, which correlates with the development of anxiety." (PMID 39851502, 2025). "For instance, FTO knockdown in the ACC induces both depressive- and anxiety-like phenotypes, possibly via downregulation of brain-derived neurotrophic factor (BDNF) signaling." (PMID 40981072, 2025). "In summary, our study demonstrates the essential role of astrocytes in stress-induced anxiety sensitivity via the BDNF and IFN signaling pathways." (PMID 40777598, 2025). "Here, male CRS rats exhibited attenuated circulating BDNF and testosterone levels, as well as low anxiety behavior with minimal alterations to HPA‐axis hormones." (PMID 40000919, 2025). "Epigenetic modifications, including DNA methylation and histone modifications, can affect the expression of BDNF and other genes, thereby influencing the anxiety phenotype." (PMID 40508224, 2025). "Overexpression of BDNF rescued repetitive self-grooming behavior and anxiety-like behavior in neonatally isolated rats." (PMID 40168357, 2025). "HET mice exhibited improved cognitive performance, reduced anxiety-like behaviors, and hepatoprotective effects following Trp supplementation, alongside increased brain serotonin levels and upregulated BDNF expression, indicative of enhanced neuroplasticity." (PMID 40182809, 2025). "BDNF and its receptor, TrkB, are well-documented modulators of synaptic function, neuronal network formation, and behaviors, including anxiety." (PMID 40777598, 2025). "The flavonoid isochlorogenic acid B in propolis helps to reduce lead-induced anxiety-like and depressive-like states in mice by reducing oxidative stress and brain inflammation while modulating the BDNF and PI3K/AKT signaling pathways." (PMID 40333577, 2025). "Activation of GABBR2 subunits alleviates the anxiety-like behaviors by promoting the BDNF signaling pathway and reversing the surface expression of Kir3 channel surface expressions in rat hippocampus." (PMID 40927314, 2025). "To explore the downstream mechanisms by which astrocytic BDNF modulates sensitivity to stress-induced anxiety-like behaviors, we employed high-throughput transcriptome sequencing." (PMID 40777598, 2025). "Our study provides critical mechanistic insights into astrocytic regulation of anxiety sensitivity and highlights astrocytic BDNF as a promising therapeutic target for stress-related anxiety disorders." (PMID 40777598, 2025). "Specifically, how astrocytic BDNF influences neuronal activity and contributes to heightened anxiety following chronic stress warrants further investigation." (PMID 40777598, 2025). "Individuals who exhibit lower anxiety symptomatology tend to have higher plasmatic BDNF levels at baseline, similarly in individuals with better cognitive function." (PMID 41164095, 2025).
Anxiety (continued). "We observed that individuals with higher cognitive scores (MoCA) and lower anxiety, profiles indicative of better brain health and higher baseline BDNF, demonstrated the steepest decline in BDNF over the winter." (PMID 41164095, 2025). "A 4-weeks adjunctive intervention of either aerobic exercise or rTMS significantly alleviates depressive and anxiety symptoms, enhances attention and executive function, and modulates serum levels of 5-HT and BDNF in adolescent inpatients." (PMID 41477617, 2025). "CRS-exposed mice exhibited significantly reduced BDNF and TrkB mRNA and protein levels, indicating a potential role of impaired BDNF-TrkB signaling in the development of anxiety-like behaviors." (PMID 40777598, 2025). "Our findings underscore the crucial role of astrocytic BDNF in anxiety sensitivity, providing insights into potential therapeutic targets for anxiety disorders." (PMID 40777598, 2025). "Previous reports have shown increased BDNF levels, along with reduced anxiety and/or attenuated stress hormone responses, and/or improved memory, following NH." (PMID 40867109, 2025). "Follow-up studies indicated that the amygdala is the critical source of BDNF linking anxiety behaviors and metabolic function." (PMID 38672441, 2024). "Temporally increased expression of pro-, mature-, and unprocessed (mutant) BDNF forms in the neonatal mPFC had an effect on anxiety and depressive-like behaviors in adolescence." (PMID 39619203, 2024). "Exercise alone increased BDNF levels, improved spatial learning and memory, and decreased anxiety‐like behaviors." (PMID 38988101, 2024). "It was proved that the early colonization of Lactobacillus contributed to alleviating anxiety by increasing the level of BDNF in the hippocampus and amygdala." (PMID 39012662, 2024). "This is supported by the finding that adult rats given intra-hippocampal BDNF experience a decrease in anxiety measured by the elevated plus maze test." (PMID 39195700, 2024). "Next, we measured the protein expression levels of BDNF in three classical brain regions known to regulate anxiety and stress: mPFC, amygdala, and hippocampus." (PMID 38672038, 2024). "The neuroprotective effect of RES via the SIRT1/AMPK/BDNF pathway contributes significantly to improved anxiety behavior." (PMID 39275174, 2024). "Mice with viral colitis and anxiety showed an improvement in anxiety-like behavior and a restoration of BDNF levels in their brains when supplemented with B. longum." (PMID 39600755, 2024). "Specifically, we observed a significant positive correlation between hippocampal BDNF expression and indicators of reduced anxiety-like behavior." (PMID 39766310, 2024). "This work illustrates a mechanism governed by BDNF and linking anxiety to changes in energy metabolism." (PMID 38672441, 2024). "Both mouse embryo culture with corticosterone and maternal preimplantation restraint stress increased anxiety-like behavior while decreasing hippocampal expression of GR and BDNF in offspring." (PMID 38727294, 2024). "Genetics also seem to influence anxiety and stress management as in the case of brain-derived neurotrophic factor (BDNF) and striatal dopamine transporter (DAT)." (PMID 38390388, 2024). "Levothyroxine alone increased BDNF levels and improved spatial learning, while exercise alone boosted BDNF levels, enhanced spatial learning and memory, and reduced anxiety‐like behaviors." (PMID 38988101, 2024). "Expression of mature BDNF increased indicators of anxiety and depressive-like behavior in the tests, expression of mutant BDNF (proBDNF_mut) increased only depressive-like behavior." (PMID 39619203, 2024). "In the present study, we found that the BDNF-TrkB signaling pathway in the mPFC plays a crucial role in the regulation of anxiety-like behaviors." (PMID 38672038, 2024).
Anxiety (continued). "Lactobacillus reuteri NK33 and Bifidobacterium adolescentis NK98 alleviate stress, depression, anxiety, and sleep disturbances through the suppression of inflammation, improvement of the gut ecosystem and increased brain-derived neurotrophic factor expression." (PMID 39439902, 2024). "Using two HD mouse models, the study found that MSC/BDNF treatment reduced striatal atrophy, alleviated anxiety, increased neurogenesis-like activity, and extended lifespan." (PMID 39200370, 2024). "In the present study, MOE treatment for two weeks reduced anhedonia, anxiety, and depressive-like behaviors and improved spatial learning and memory with increased serum BDNF concentration in the HFD-fed rats." (PMID 40255947, 2024). "BDNF is a crucial neurotrophin that plays a vital role in regulating mood and anxiety‐related behaviors." (PMID 38988101, 2024). "Contrary to the toxic effect of β-Alanine, there are studies suggesting that β-Alanine supplementation can reduce anxiety in both young and older rats by increasing the expression of brain derived neurotrophic factor (BDNF) in the subregion of the hippocampus." (PMID 38519946, 2024). "A maternal PTU‐induced hypothyroidism model led to increased anxiety‐like behaviors, impaired spatial navigation, and reduced hippocampal BDNF levels in male offspring rats." (PMID 38988101, 2024). "Meanwhile, it was indicated that some anti-anxiety drugs improve anxiety symptoms in rats by increasing the expression level of BDNF mRNA and protein in the cells of rat brains." (PMID 39012662, 2024). "The administration of Bifidobacterium adolescentis in mice subjected to CRS not only reduces anxiety and depressive-like behaviors and increases BDNF expression levels, but also reverses the dysbiosis of the gut microbiota induced by CRS." (PMID 39286351, 2024). "Up-regulation of BDNF mRNA in the dentate region of the hippocampus in the germ-free mice is consistent with literature identifying a role for this molecule in anxiety-like behaviors." (PMID 38756771, 2024). "The impact of BDNF on anxiety symptoms should also be explored, considering its interference with antidepressant response." (PMID 39408702, 2024). "After 14 days of interventions, anxiety‐like behaviors, spatial learning and memory, and hippocampal brain‐derived neurotrophic factor (BDNF) levels were evaluated." (PMID 38988101, 2024). "EF-2001 attenuated anxiety-like behavior by reducing serum LPS and corticosterone levels linked to the improvement of UC symptoms and by facilitating the CAMKII/CREB/BDNF-Drebrin pathways in the PFC." (PMID 38769131, 2024). "In this anxiety model, the increased expression of BDNF reflects the neuroprotective properties of resveratrol." (PMID 39275174, 2024). "BDNF is a common downstream mediator of environmental factors that enhance anxiety- and depressive-like behaviors." (PMID 38796504, 2024). "Firstly, BDNF re-expression in the amygdala of Bdnflox/lox;Emx1-cre mutant mice reversed the previously observed alterations in anxiety-related behavior and metabolic function." (PMID 38672441, 2024). "On the contrary, however, Fmr1 KO mice after fluoxetine treatment have reduced anxiety but enhanced explorative activity during the open field test, with abnormal changes of BDNF/TrkB signaling in the hippocampus." (PMID 38716113, 2024). "Vlx has exhibited superior beneficial effects in alleviating anxiety-like behaviors, learned fear, stress-related behaviors, and promoting the expression of BDNF in stressed male rats." (PMID 38435986, 2024). "A pre and postnatal PTU‐induced experimental model of hypothyroidism increased anxiety‐like behaviors, impaired cognitive functions, and decreased hippocampal BDNF levels in male offspring rats." (PMID 38988101, 2024). "The primary predictor variable was serum BDNF level and the second predictor variable was anxiety scores before and after operation in patients." (PMID 38907644, 2024).
Anxiety (continued). "Studies in animals have demonstrated that levothyroxine-induced hyperthyroidism in rats significantly elevates serum FT3 and FT4 levels, increases brain 5-HT expression, and reduces hippocampal BDNF content, leading to pronounced anxiety-like behaviors." (PMID 39717701, 2024). "We observed that mice subjected to the HFD exhibited reduced anxiety levels, which correlated with alterations in the BDNF-TrkB signaling pathway in the mPFC." (PMID 38672038, 2024). "We aimed to elucidate the relationship between HFD consumption and anxiety, with a focus on the role of BDNF in the medial prefrontal cortex (mPFC)." (PMID 38672038, 2024). "A pre and postnatal PTU‐induced model of hypothyroidism increased anxiety‐like behaviors, impaired spatial learning and memory, and decreased hippocampal BDNF levels in male offspring rats." (PMID 38988101, 2024). "The improvement effects of BRL-50481 were blocked by ANA-12, indicating that the PDE7 inhibitor reduced fear conditioning responses and anxiety-like behaviors in SPS mice at least partially through the BDNF/TrkB pathway." (PMID 39092219, 2024). "In HD, BDNF delivered through mesenchymal stem cells reduced striatal atrophy, alleviated anxiety, increased neurogenesis-like activity, and extended lifespan in murine models." (PMID 39200370, 2024). "The secondary outcome variable were anxiety scores and BDNF changes before and after the operation in patients." (PMID 38907644, 2024). "Temporary increase in expression of mature BDNF (LV-BDNF) in the mPFC had a significant effect on anxiety." (PMID 39619203, 2024). "Compared to females, male GF mice have greater perturbations to the serotonergic system both peripherally and centrally and mitigated BDNF expression, which was accompanied by alterations in anxiety-like behavior." (PMID 39712189, 2024). "In the BACHD mouse model, their direct delivery to the striatum diminished mutant Htt levels, ameliorated mitochondrial dysfunction, restored BDNF expression, and improved motor and anxiety-like phenotypes." (PMID 38374466, 2024). "It is noteworthy that Adlercreutzia was negatively correlated with anxiety-like behavior, positively with alcohol preference, and negatively with the expression of brain-derived neurotrophic factor (BDNF) and Gabra1 in the prefrontal cortex." (PMID 39337263, 2024). "In conclusion, we found that increased expression of mature BDNF (LV-BDNF) at P5-P8 resulted in increased anxiety and depressive-like behaviors at P30." (PMID 39619203, 2024). "The role of BDNF in anxiety is controversial, and BDNF expression was observed to be reduced in the PLWH." (PMID 38563030, 2024). "Simultaneously, SCFAs derived from microbes can also enhance the secretion of mature BDNF by activating the Sigmar-1 receptor (SigR1), thereby ameliorating anxiety and depression-like behaviors." (PMID 39717701, 2024). "Data on the age and gender of patients and the preoperative and postoperative variables (anxiety scores and serum BDNF level) were collected." (PMID 38907644, 2024). "Mice genetically modified to overexpress BDNF show anxiety-like behavior when exposed to chronic immobilization stress." (PMID 38539677, 2024). "Anxiety behavior, along with decreased hippocampal BDNF, is also provoked by hyperalgesia, such as in the case of low back pain." (PMID 39275174, 2024). "Temporal alteration of BDNF signaling in the neonatal mPFC had a significant effect on anxiety and depressive-like behaviors in adolescence." (PMID 39619203, 2024). "Recent work has demonstrated that impaired BDNF signaling in the dentate gyrus of adult mice results in a marked increase in anxiety-like behavior." (PMID 38756771, 2024). "In a mouse model of anxiety and sleep disruption, Hericium erinaceus mycelium induced an antidepressant-like effect modulating BDNF/TrkB/PI3K/Akt/GSK-3β pathways and ameliorated the rodent anxiety and sleep disturbance." (PMID 37592816, 2024).
Anxiety (continued). "The study was completely blinded because the investigators who determined the BDNF results and anxiety scores were different and the patients were numerically named." (PMID 38907644, 2024). "In the current study, we showed that hippocampal overexpression of TrkB.T1 further reduced the BDNF level, in line with the increase in depressive-like behavioral traits observed in the tail suspension test and increase in anxiety." (PMID 37761014, 2023). "This was the first case-controlled and prospective study to explore the predictive roles of serum BDNF and anxiety-related variables in changes in somatic symptoms measured by PHQ-15 in patients with PD." (PMID 37533888, 2023). "MVPA can increase BDNF levels in the central nervous system, improving anxiety and depressive symptoms." (PMID 37854249, 2023). "In contrast to our data in TRD, in a study including only 39 patients with MDD, plasma BDNF levels were negatively correlated with the severity of depressive and anxiety symptoms." (PMID 37759825, 2023). "The damage was possibly attributed to iron‐induced downregulation of proprotein convertase furin and subsequently decreased maturation of brain‐derived neurotrophic factor (BDNF), thus contributing to memory decline and anxiety‐like behavior of mice." (PMID 37545321, 2023). "This supplementation also elevated the expression of brain-derived neurotrophic factor mRNA, indicating protective effects against the neurological stresses of anxiety." (PMID 37867495, 2023). "We aimed to explore the predictive role of serum BDNF and anxiety-related variables in changes in somatic symptoms post-escitalopram treatment in panic disorder (PD) patients." (PMID 37533888, 2023). "Several lines of research highlight the need to explore the relationship between BDNF and anxiety peripheral levels as well as the importance of other biomarkers such as NSE and S100B." (PMID 38055476, 2023). "There is a significant reduction in anxiety and depressive symptoms with an increase in BDNF levels." (PMID 38143611, 2023). "Exercise alone or in combination with fluoxetine restored the malevolent effects of SPS on anxiety-like behavior, prefrontal and serum BDNF, fear conditioning, and extinction." (PMID 36647145, 2023). "Here, we first reported that heterozygous BDNF+/Met mice displayed anxiety-like behaviors in both sexes, which demonstrates that the Met allele in the BDNF gene plays a key role in genetic predisposition to anxiety." (PMID 37205980, 2023). "Recent studies have shown that RES can alleviate anxiety-like behavior and decrease brain-derived neurotrophic factor (BDNF) levels, which are typically decreased in stressed rats in experimental PTSD models." (PMID 37762647, 2023). "Studies have found that the probiotic B. longum NCC3001 reduced the excitability of enteric neurons and normalized the levels of hippocampal brain-derived neurotrophic factor, resulting in anti-anxiety effects." (PMID 38057706, 2023). "For example, BDNF knockout mice, which have low level of BDNF in the forebrain, showed high degrees of anxiety and it has been demonstrated that overexpression of BDNF in hippocampus decreased anxiety‐like behaviors." (PMID 36942730, 2023). "The overexpression of serum CDCA over-activates intestinal FXR receptors, resulting in an imbalance in the FGFs/FGFRs system that impacts the BDNF-TrkB signal pathway, which finally culminates in anxiety-like behavior." (PMID 38075046, 2023). "In the following studies, we will conduct in-depth studies on the specific mechanism of WP + CP on anxiety-relieving and memory improvement, particularly the serotonin and BDNF pathways." (PMID 37867495, 2023). "Contrary to the hippocampus, an increase in the level of BDNF in the basolateral amygdala and amygdala can induce anxiety." (PMID 37396946, 2023). "Following single prolonged stress, inhibition of miR-142-5p resulted in decreased anxiety-like behaviors and memory deficits, as well as increased expression of Npas4 and BDNF." (PMID 36979479, 2023).